RSPH9 (radial spoke head component 9)
Description:
Functions as part of axonemal radial spoke complexes that play an important part in the motility of sperm and cilia. Essential for both the radial spoke head assembly and the central pair microtubule stability in ependymal motile cilia (By similarity). Required for motility of olfactory and neural cilia and for the structural integrity of ciliary axonemes in both 9+0 and 9+2 motile cilia (By similarity).
Synonyms: C6orf206; MRPS18AL1; FLJ30845; CILD12
Tractability: Small molecule: a structure with a bound ligand is known.
Gene: Protein-coding gene on chromosome 6 (43,644,229 to 43,672,604, forward strand). Ensembl gene ENSG00000172426.
Subcellular location: Cytoplasm, cytoskeleton, cilium axoneme; Cytoplasm, cytoskeleton, flagellum axoneme; Cell projection, kinocilium
Subcellular location (Human Protein Atlas): End piece; Mid piece; Principal piece; Acrosome; Equatorial segment
Gene Ontology:
Molecular function: protein binding
Biological process: axoneme assembly; cilium movement; axonemal central apparatus assembly; cilium movement involved in cell motility; flagellated sperm motility; motile cilium assembly; radial spoke assembly
Cellular component: 9+2 motile cilium; axoneme; cilium; motile cilium; radial spoke; radial spoke head; sperm flagellum; kinocilium; radial spoke head 1; radial spoke head 3
Genetic constraint (gnomAD): Loss-of-function variants: 27 observed, 28.29 expected, observed/expected ratio (o/e) 0.95, 90% interval 0.7 to 1.32. The upper end of that interval is the gene's LOEUF score, 1.32, which puts it in group 5 of 6, group 1 being the genes least tolerant of losing a copy. Missense variants: 347 observed, 380.01 expected, observed/expected ratio (o/e) 0.91, 90% interval 0.84 to 1. Synonymous variants: 145 observed, 156.72 expected, observed/expected ratio (o/e) 0.93, 90% interval 0.81 to 1.06.
Gene-disease validity (ClinGen):
ClinGen rates the evidence that RSPH9 causes each of these diseases.
primary ciliary dyskinesia 12 (autosomal recessive): Definitive.
Homologues: Orthologues: macaque RSPH9 (99% identical), pig RSPH9 (94% identical), dog RSPH9 (92% identical), mouse Rsph9 (92% identical), rabbit RSPH9 (91% identical), rat Rsph9 (91% identical), guinea pig RSPH9 (87% identical), chimpanzee RSPH9 (79% identical), zebrafish rsph9 (55% identical), tropical clawed frog rsph9 (54% identical), Drosophila melanogaster Rsph9 (34% identical).
Diseases named in the same sentence as RSPH9 in open-access papers:
RSPH9 is named in the same sentence as 21 diseases in open-access papers, as found by Europe PMC text mining. Sharing a sentence is not in itself a finding about the gene and the disease. The quoted sentences say what the papers report.
primary ciliary dyskinesia (7 papers, 2015 to 2025). A rare, genetically heterogeneous, primarily respiratory disorder characterized by chronic upper and lower respiratory tract disease. "Mutations of Rsph9 have been previously shown to cause primary ciliary dyskinesia with central microtubule pair abnormalities." (PMID 38251009, 2024). "However, mutations in RSPH9 cause primary ciliary dyskinesia (PCD; MIM 244400) in human, which is characterized by phenotypic heterogeneity and lacks a suitable “gold standard” diagnostic test." (PMID 32709945, 2020). "RSPH9-associated primary ciliary dyskinesia has a wide phenotypic variability in humans." (PMID 32709945, 2020). "The genetic testing of whole-exome sequences (WES) confirmed a homozygous variant c.804_806del, p.(Lys268del) in the RSPH9 gene that causes primary ciliary dyskinesia (PCD)." (PMID 36059358, 2022). "Several genes (ARMC4, SP2, LRRC46, RSPH9, and ZMYND10) assigned to associations are involved in primary ciliary dyskinesia (PCD), an autosomal recessive inherited disease." (PMID 35052452, 2022). "Among 32 genes in which defects lead to primary ciliary dyskinesia, six (Dnaic2, Ccdc40, Armc4, Ccdc164/DRC1, Rsph9, Ccdc11) are strongly downregulated in Rfx2-/- testes at both time points, and three others only at P30 (Ccdc65, Zmynd10, Ccno)." (PMID 26162102, 2015).
Hydrocephalus (3 papers, 2020 to 2023). Hydrocephalus is an active distension of the ventricular system of the brain resulting from inadequate passage of CSF from its point of production within the cerebral ventricles to its point of absorption into the systemic circulation. "Our results collectively suggested that RSPH9 is essential for ciliary structure and motility of mouse ependymal cilia, and its deletion causes the pathogenesis of hydrocephalus." (PMID 32709945, 2020). "The hydrocephalus caused by Rsph9 deletion was accompanied by astrogliosis and microgliosis in the cortex." (PMID 32709945, 2020). "Altogether, these results suggest that in P8 Rsph9−/− mice, hydrocephalus is associated with severe pathological reactions, inflammation reactions and myelination disorders." (PMID 32709945, 2020). "In this study, we show that Rsph9-deficient mice developed severe hydrocephalus with postnatal ventriculomegaly and severe sinusitis." (PMID 32709945, 2020). "RSPH1, RSPH4A, and RSPH9 knockout mouse models recapitulated the PCD phenotypes such as hydrocephalus and impaired mucociliary clearance." (PMID 38091523, 2023). "The occurrence of PCD and hydrocephalus has been reported in the past and has been shown to be associated with mutations in various genes (DNAI1, DNAH5, DNAH11, DNAI2, KTU, and RSPH9/4A)." (PMID 33999288, 2021). "Here, we show that deletion of the Rsph9 gene leads to the development of hydrocephalus in the early postnatal period." (PMID 32709945, 2020). "Defects in Rsph9−/− ependymal cells can lead to disruption of the pattern of cilia beating and can give rise to hydrocephalus." (PMID 32709945, 2020). "To characterize the temporal feature of hydrocephalus in mice with the Rsph9 deletion, we compared sagittal sections of the developing brain between P0 and P7 in wild-type and Rsph9−/− mouse pups." (PMID 32709945, 2020). "Our study reveals the role of RSPH9 in hydrocephalus pathogenesis and ependymal cilia motility in the developing mouse brain." (PMID 32709945, 2020). "In addition, hydrocephalus in Rsph9−/− mice results in the development of astrogliosis, microgliosis and cerebrovascular abnormalities." (PMID 32709945, 2020). "Hydrocephalus in Rsph9−/− mice also attenuated the expression of myelin basic protein (MBP), which is a marker of myelinating glia, but it enhanced the expression of oligodendrocyte transcription factor 2 (OLIG2), which is a marker of oligodendrocyte progenitor cells and mature oligodendrocytes." (PMID 32709945, 2020). "Furthermore, deletion of Rsph9 can result in the development of brain dysfunction and progressive hydrocephalus during postnatal development in mice." (PMID 32709945, 2020).
Infertility (3 papers, 2022 to 2025). "Among women with known genetic results, those with infertility had DNAH5, DNAAF3, ZMYND10, CCDC40, RSPH9 and HYDIN mutations." (PMID 40142748, 2025). "We identified ten infertile male individuals with pathogenic variants in CCDC39 (one) and CCDC40 (two) encoding ruler proteins, RSPH1 (two) and RSPH9 (one) encoding radial spoke head proteins, and HYDIN (two) and SPEF2 (two) encoding CP-associated proteins, respectively." (PMID 36873931, 2023). "In the RSPH family, RSPH9 and RSPH4A encoded a generic component of the radial spoke heads of cilia, and mutation of these genes caused central microtubular pair abnormalities and infertility." (PMID 35955660, 2022).
bronchiectasis (2 papers, 2023 to 2025). Segmental, irreversible dilation of the bronchial tree resulting in the accumulation of secretions which leads to obstruction. "The homozygous RSPH9 mutation identified in this patient impairs effective ciliary movement, leading to recurrent respiratory infections, persistent airway inflammation, and bronchiectasis." (PMID 40981013, 2025). "RSPH9-mutant individual OP-2491 II1, who presented with chronic destructive lung disease, underwent a middle lobe resection of the lung, due to bronchiectasis." (PMID 36873931, 2023).
male infertility (2 papers, 2022 to 2023). The inability of the male to effect fertilization of an ovum after a specified period of unprotected intercourse. "We demonstrate for the first time that pathogenic variants in RSPH1 and RSPH9 cause male infertility due to sperm cell dysmotility and abnormal flagellar RSPH1 and RSPH9 composition." (PMID 36873931, 2023). "Male infertility caused by the RSPH1 or RSPH9 variant has been clarified." (PMID 35812741, 2022). "Variants in RSPH1, RSPH3, and RSPH9 genes have been reported to cause male infertility in humans." (PMID 35812741, 2022).
respiratory infections (2 papers, 2018 to 2025). "Mutations in members of this gene family (RSPH9 and RSPH4A) are specifically linked to recurrent respiratory infections and male subfertility due to impaired sperm motility." (PMID 29391579, 2018).
hepatocellular carcinoma (1 paper, 2019). A malignant tumor that arises from hepatocytes. "RSPH9 (radial spoke head 9 homolog) was significantly hypermethylated and downregulated in the hepatocellular carcinoma (HCC) and epigenetic silencing of RSPH9 may be associated with hepatocellular carcinoma." (PMID 31886214, 2019).
Respiratory tract infection (1 paper, 2019). An infection of the upper or lower respiratory tract. "This is exemplified by one case (70.1) suffering from recurrent respiratory tract infections for which exome sequencing identified a homozygous pathogenic variant in the first amino acid of the protein RSPH9 p.(M1T/M1T)." (PMID 31203817, 2019).
sinusitis (1 paper, 2020). An acute or chronic inflammatory process affecting the mucous membranes of any sinus cavity. "However, Rsph9−/− mice developed severe neurological disorders and sinusitis." (PMID 32709945, 2020).
varicocele (1 paper, 2015). A condition characterized by the dilated tortuous veins of the spermatic cord with a marked left-sided predominance. "In our study, we found that RSPH9 was underexpressed in the unilateral varicocele group." (PMID 25890347, 2015).
adenocarcinoma (1 paper, 2019). A common cancer characterized by the presence of malignant glandular cells. "The expression levels of RRAGB, RSPH9, RPS6KL1, RXFP1, and RTL1 mRNA were significantly lower and the RRM2 mRNA level was significantly higher in the high-risk group than those in the low-risk group in NSCLC adenocarcinoma of GSE11969." (PMID 31886214, 2019). "This signature and the genes RRAGB, RSPH9, RPS6KL1, RXFP1, RRM2, and RTL1 included in this model are independent biomarkers for prediction of overall survival of NSCLC adenocarcinoma." (PMID 31886214, 2019). "Our six-gene prognostic signature for NSCLC adenocarcinoma include RRAGB, RSPH9, RPS6KL1, RXFP1, RRM2, and RTL1 genes which are not contained in the previous gene signatures." (PMID 31886214, 2019).
cancer (1 paper, 2019). A tumor composed of atypical neoplastic, often pleomorphic cells that invade other tissues. "The model signature genes RSPH9, RPS6KL1, RXFP1, and RTL1 have been revealed to be involved in cancer activity." (PMID 31886214, 2019).
RSPH9 also shares sentences with these, for which no sentence is quoted: asthenozoospermia (1 paper); breast carcinoma (1); Hearing impairment (1); infection (1); lung adenocarcinoma (1); Neonatal respiratory distress (1); neurological disorders (1); situs inversus (1); Ventriculomegaly (1).